YWHAB (tyrosine 3-monooxygenase/tryptophan 5-monooxygenase activation protein beta)
Description:
Adapter protein implicated in the regulation of a large spectrum of both general and specialized signaling pathways. Binds to a large number of partners, usually by recognition of a phosphoserine or phosphothreonine motif. Binding generally results in the modulation of the activity of the binding partner. Negative regulator of osteogenesis. Blocks the nuclear translocation of the phosphorylated form (by AKT1) of SRPK2 and antagonizes its stimulatory effect on cyclin D1 expression resulting in blockage of neuronal apoptosis elicited by SRPK2. Negative regulator of signaling cascades that mediate activation of MAP kinases via AKAP13.
Synonyms: KCIP-1; GW128; HEL-S-1; HS1; YWHAA
Tractability: Small molecule: a structure with a bound ligand is known; it has a binding pocket of medium quality. PROTAC: UniProt records ubiquitination sites on it; ubiquitination databases record sites on it; its protein half-life has been measured.
Gene: Protein-coding gene on chromosome 20 (44,885,676 to 44,908,532, forward strand). Ensembl gene ENSG00000166913.
Subcellular location: Cytoplasm; Melanosome; Vacuole membrane
Subcellular location (Human Protein Atlas): Cytosol
Pathways (Reactome):
Disease: Gain-of-function MRAS complexes activate RAF signaling; Paradoxical activation of RAF signaling by kinase inactive BRAF; SARS-CoV-1 targets host intracellular signalling and regulatory pathways; SARS-CoV-2 targets host intracellular signalling and regulatory pathways; SHOC2 M1731 mutant abolishes MRAS complex function; Signaling by BRAF and RAF1 fusions; Signaling by RAF1 mutants; Signaling by high-kinase activity BRAF mutants; Signaling by moderate kinase activity BRAF mutants; Signaling downstream of RAS mutants
Signal Transduction: ARMS-mediated activation; Frs2-mediated activation; MAP2K and MAPK activation; MTOR signalling; Negative regulation of MAPK pathway; RAF activation; RHO GTPases activate PKNs; Signaling by Hippo
Gene expression (Transcription): Regulation of localization of FOXO transcription factors
Metabolism of RNA: Butyrate Response Factor 1 (BRF1) binds and destabilizes mRNA; Tristetraprolin (TTP, ZFP36) binds and destabilizes mRNA
Cell Cycle: Chk1/Chk2(Cds1) mediated inactivation of Cyclin B:Cdk1 complex
Developmental Biology: Transcriptional and post-translational regulation of MITF-M expression and activity
Immune System: Rap1 signalling
Programmed Cell Death: Activation of BAD and translocation to mitochondria
Vesicle-mediated transport: Translocation of SLC2A4 (GLUT4) to the plasma membrane
Gene Ontology:
Molecular function: cadherin binding; enzyme binding; histone deacetylase binding; identical protein binding; phosphoprotein binding; phosphoserine residue binding; protein binding; protein domain specific binding; protein kinase inhibitor activity; protein phosphatase inhibitor activity; protein sequestering activity; protein-containing complex binding
Biological process: negative regulation of G protein-coupled receptor signaling pathway; negative regulation of protein import into nucleus; positive regulation of transcription by RNA polymerase II; intracellular protein localization; negative regulation of DNA-templated transcription
Cellular component: cytoplasm; cytosol; extracellular exosome; focal adhesion; membrane; nucleus; perinuclear region of cytoplasm; vacuolar membrane; melanosome; protein-containing complex; transcription repressor complex
Genetic constraint (gnomAD): Loss-of-function variants: 2 observed, 25.57 expected, observed/expected ratio (o/e) 0.0782, 90% interval 0.031 to 0.25. The upper end of that interval is the gene's LOEUF score, 0.25, which puts it in group 1 of 6, group 1 being the genes least tolerant of losing a copy. Missense variants: 147 observed, 302 expected, observed/expected ratio (o/e) 0.49, 90% interval 0.43 to 0.56. Synonymous variants: 102 observed, 105.99 expected, observed/expected ratio (o/e) 0.96, 90% interval 0.82 to 1.13.
Homologues: Orthologues: chimpanzee YWHAB (100% identical), guinea pig YWHAB (100% identical), mouse Ywhab (99% identical), rat Ywhab (98% identical), rabbit YWHAB (95% identical), pig YWHAB (94% identical), macaque YWHAB (93% identical), zebrafish ywhaba (91% identical), tropical clawed frog ywhab (88% identical), zebrafish ywhabb (87% identical), Drosophila melanogaster 14-3-3zeta (78% identical), Caenorhabditis elegans par-5 (76% identical), and 1 more. Paralogues in human: YWHAZ (87% identical), YWHAQ (81% identical), YWHAG (76% identical), YWHAH (76% identical), YWHAE (68% identical), SFN (67% identical).